TPO (thyroid peroxidase)
Diseases named in the same sentence as TPO in open-access papers (continued):
Sharing a sentence is not in itself a finding about the gene and the disease.
autoimmune thyroid disease (continued). "Autoimmune thyroid disease (AITD) is one of the most common organ-specific autoimmune diseases, which is characterized by endocrine abnormalities and an elevated presence of thyroid antibodies, such as antibodies against thyroid peroxidase (TPOAbs) and antibodies against thyroglobulin (TgAbs)." (PMID 29312834, 2018). "While several controlled studies revealed a higher prevalence of overt autoimmune thyroid diseases and greater positivity of anti-thyroid peroxidase (TPO) among pemphigus patients, other studies did not demonstrate a significant association between pemphigus and clinical AITD." (PMID 29900171, 2018). "Besides these we have not determined thyroid autoimmunity related parameters like serums Tg-Ab and TPO-Ab and ultrasound echogenicity in our patients." (PMID 28638825, 2017). "The effects of I2 on immune responses of Tg and TPO antigens in thyroid autoimmunity might not be completely the same." (PMID 28536577, 2017). "However, apart from SREAT, autoimmune thyroiditis (AIT) patients who are in an euthyroid state, suffer from mild to severe cognitive alterations correlating with serum levels of anti-thyroid antibodies, in particular anti-TPO and anti- TG antibodies." (PMID 28529699, 2017). "Thyroid peroxidase (TPO) antibodies are detectable in ~95% of patients with Hashimoto's thyroiditis, and thyroglobulin TG antibodies are positive in approximately 60% of adult patients with chronic thyroiditis (less often in children with thyroid autoimmune disease)." (PMID 25114812, 2014). "Our study suggested that a larger series of patients did not change the result using anti-TPO, which is more sensitive and specific in determining the autoimmune thyroiditis, and this supported the data raising questions about the place of BD in autoimmune diseases." (PMID 23476155, 2013). "In this patient, the diagnosis of autoimmune thyroiditis was made on the basis of the presence of anti-thyroid peroxidase antibodies and the absence of evidence of another etiology for hyperthyroidism, such as Graves' disease, multi-nodular goiter or toxic adenoma." (PMID 21722403, 2011). "Although TPO antibodies were not assessed in the present case, simultaneous measurement of TPO and TRAb may yield a more comprehensive evaluation of post-vaccination thyroid autoimmunity." (PMID 41409965, 2025). "In fact, TPO-Ab and Tg-Ab may be positive in 10–15% of people without autoimmune thyroid diseases." (PMID 34986823, 2022). "Normal levels of serum free T4, TSH and Tg, and negative in anti-TPO antibody testing with no obvious nodule in thyroid ultrasonography (data not shown) were demonstrated to exclude any thyroid disorders such as thyroid nodules, autoimmune thyroid disease, and cancer history." (PMID 26684026, 2016). "Anti-TPO antibody testing, which is important for distinguishing transient SCH from early autoimmune thyroid disease, was also not performed." (PMID 40502886, 2025). "A significant limitation is the absence of preprocedural TSI and TPO antibody measurements, as initial ultrasound and thyroid function tests (TSH, FT4) showed no signs of thyroid autoimmunity prior to RFA." (PMID 39911620, 2025). "Fourth, Serum concentrations of serum thyroid peroxidase (TPO) and thyroglobulin antibodies were not further determined to assess the prevalence of autoimmune thyroid disease." (PMID 38281045, 2024). "While anti-TPO antibodies are not exclusive to SREAT and can be found in other autoimmune thyroid diseases, their detection in the context of neurological symptoms is highly suggestive of SREAT." (PMID 39473654, 2024). "In addition, determination of anti-TPO threshold values in prognostic modeling of ART clinical efficiency, i.e., clinical pregnancy and live birth rates, could be another promising way to increase the success rate of infertility treatment in women with autoimmune thyroid disease." (PMID 36902134, 2023).
autoimmune thyroid disease (continued). "Additionally, the lack of anti- TPO data limits the ability to explore the full spectrum of thyroid abnormalities in PCOS patients and restricts comparisons with other studies where autoimmune thyroid markers were measured." (PMID 40654392, 2024). "Since, anti-thyroid peroxidase antibody (anti-TPO) was not assayed in the population, high prevalence of thyroid autoimmunity may also contribute for high rate of thyroid dysfunction in the study population." (PMID 26819633, 2016).
Hashimoto thyroiditis (343 papers, 2005 to 2026). An autoimmune disorder caused by the production of autoantibodies against thyroid tissue. "In Hashimoto’s thyroiditis, selenium has been linked to decreases in anti-TPO and anti-Tg antibodies as well as slight improvements in thyroid structure and function." (PMID 41157173, 2025). "High thyroid peroxidase antibody (anti-TPO) titers have been associated with a reduced risk of thyroid malignancy in patients with Hashimoto’s thyroiditis." (PMID 41155761, 2025). "These cases suggest a mechanism involving thyroid trauma, the release of thyroid antigens, and the subsequent generation of TPO antibodies linked to Hashimoto's thyroiditis or thyrotropin receptor antibodies (TSI) associated with Graves' disease." (PMID 39911620, 2025). "His father (P18) carried the same variant but was asymptomatic, later developing Hashimoto thyroiditis (anti-TPO > 100)." (PMID 41142805, 2025). "The positive anti-TPO antibodies show that the patient likely had the genetic predisposition for chronic thyroiditis which remained dormant up until the oncology therapy triggers (CXT, RXT, and IXT)." (PMID 39021640, 2024). "The primary cause of subclinical hypothyroidism is chronic autoimmune thyroiditis, specifically linked to anti-TPO antibodies, a condition known as Hashimoto's thyroiditis." (PMID 38344555, 2024). "Hashimoto’s thyroiditis, also known as chronic lymphocytic thyroiditis, is primarily associated with the presence of thyroid peroxidase antibodies and, to a lesser extent, thyroglobulin antibodies." (PMID 39776440, 2024). "The fact that the patient had a positive thyroid peroxidase Ab approximately 11 times greater than normal with a TSH greater than 150 mclnt Unit/mL supported the association of Hashimoto’s thyroiditis and fibrillary glomerulonephritis." (PMID 39618600, 2024). "Increased anti-thyroid peroxidase antibodies (anti-TPO) are the hallmark of Hashimoto’s thyroiditis diagnosis." (PMID 38628593, 2024). "Second, TPO antigens reflect the presence or increased risk of thyroid immune disorders such as Graves' disease and Hashimoto's disease." (PMID 36600266, 2023). "Anti-TPO positivity is a marker of autoimmune thyroid disorders (Graves’ Disease and Hashimoto Thyroiditis) and is linked with male and female subfertility, even in subjects with biochemically normal thyroid function." (PMID 37763034, 2023). "Anti-TPO antibody titers and thyroid volume appear to be associated with vitamin D insufficiency in Hashimoto’s disease, and supplementation was linked to a decrease in antibody titers and TSH levels." (PMID 36904227, 2023). "Simultaneous detection of two antibodies that have been associated with thyroid ADs, and especially Hashimoto’s thyroiditis, i.e., anti-thyroglobulin (anti-TG) and anti–thyroid peroxidase (anti-TPO) model autoantibodies, was reported." (PMID 37571553, 2023). "Another study evaluated the association of several TPO SNPs and the TPOAb levels in patients with autoimmune hypothyroidism." (PMID 36980259, 2023). "The presence of TPO-antibodies is typically associated with thyroid disorders such as Hashimoto’s disease." (PMID 37511088, 2023). "Selenium supplementation in Hashimoto’s thyroiditis was associated with the decreased levels of anti-thyroid peroxidase antibody and improved thyroid ultrasound structure." (PMID 37033262, 2023). "In Hashimoto’s disease, vitamin D deficiency appears to be correlated with a higher titer of anti-TPO antibodies and with thyroid volume, and supplementation was associated with reduction of antibodies in some studies." (PMID 35208518, 2022). "DH is associated with AITD (mainly Hashimoto thyroiditis) and up to 48% of DH patients were found positive for anti-TPO autoantibodies in several studies." (PMID 36225612, 2022).
Hashimoto thyroiditis (continued). "Hashimoto’s thyroiditis (HT) is an autoimmune inflammatory disease associated with the presence of autoantibodies against thyroglobulin (TG) and thyroid peroxidase (TPO), and with lymphocytic infiltration of the thyroid gland." (PMID 36614854, 2022). "Our patient’s high anti-thyroid peroxidase antibody level indicated Hashimoto’s thyroiditis as the underlying etiology." (PMID 35530928, 2022). "Diagnostic criteria of HT were as follows: thyroid peroxidase antibody (+) and postoperative histopathology of Hashimoto’s disease." (PMID 34986823, 2022). "Anti-TPO levels were significantly high in subjects with folate deficiency; high levels of serum anti-TPO and anti-Tg are linked with the development of autoimmune hypothyroidism (Hashimoto thyroiditis)." (PMID 35140907, 2021). "As shown by a meta-analysis covering 22 studies, obesity is statistically significantly associated with Hashimoto’s disease (p = 0.022) and high levels of anti-TPO (p = 0.001)." (PMID 33808030, 2021). "Thyroid-stimulating hormone levels and anti-thyroid peroxidase antibodies were found to be elevated, suggesting an underlying etiology of Hashimoto's thyroiditis." (PMID 34040922, 2021). "Anti-TPO antibody levels were found to be significantly higher in patients with Vitamin D insufficiency or deficiency, compared to patients with Hashimoto’s thyroiditis with normal Vitamin D levels." (PMID 35317375, 2021). "Autoantigens associated with Hashimoto’s thyroiditis are derived from thyroglobulin and TPO, critical proteins within thyroxine (T4) synthesis." (PMID 32433950, 2020). "In the past, probably because Tg-abs was less specific for lymphocytic thyroiditis, TPO-abs was considered better marker for lymphocytic thyroiditis than Tg-abs." (PMID 31791284, 2019). "This study demonstrates a clear association between psoriasis and Hashimoto’s thyroiditis in the form of a significantly higher prevalence of TPO Ab, Tg Ab, hypo-echogenicity, pseudo-nodularity, and increased vascularity." (PMID 31157131, 2019). "Autoantibodies to TPO and/or thyroglobulin are invariably associated with Hashimoto’s thyroiditis, but with a lower prevalence in Graves’ disease." (PMID 28620373, 2017). "The association of thyroid peroxidase antibody (TPOAb) and endothelium-dependent arterial dilation in euthyroid Hashimoto's thyroiditis patients also has been reported." (PMID 26770196, 2015). "TPO encodes a primary autoantigen in both Hashimoto's Thyroiditis (HT) and Graves' Disease (GD); PTPRN2, and FLG encode primary autoantigens in Type-1 Diabetes (T1D) and Rheumatoid Arthritis (RA) respectively." (PMID 24988487, 2014). "Our predictions give strong support for thyroid-specific expression of the genes TPO (strong support) and TG (strong support) encoding proteins malfunctions of which cause Hashimoto's thyroiditis (OMIM ID 140300)." (PMID 23950964, 2013). "Regulatory T cells (Treg) are a major factor in intermolecular immune response expansion, both from TSHR to TPO and Tg and alteration of hyperthyroid into Hashimoto's thyroiditis with massive thyroid lymphocytic infiltration, which causes hypothyroid state." (PMID 24198979, 2013). "Biochemical testing of thyroid function and Thyroid Peroxidase Antibody was in-keeping with an associated Hashimoto's thyroiditis." (PMID 21048843, 2010). "Circulating antibodies to thyroid peroxidase are positive in 60–80% of patients suggesting underlying lymphocytic thyroiditis as a predisposing factor." (PMID 16336672, 2005). "While thyroid peroxidase (TPO) and thyroglobulin (Tg) antibodies are more strongly associated with Hashimoto’s thyroiditis, TRAb are typically present in Graves’ disease, though they may occasionally be detected in Hashimoto’s." (PMID 41217125, 2025).
Hashimoto thyroiditis (continued). "The destruction of thyroid cells in Hashimoto’s thyroiditis (HT) is linked to several immune processes, both cellular and antibody-mediated, which involve thyroid autoantibodies against thyroid peroxidase (TPO) and thyroglobulin (Tg)." (PMID 40937419, 2025). "Thyroid peroxidase antibodies (anti-TPO) are strongly associated with autoimmune hypothyroidism." (PMID 40255503, 2025). "This hypothesis is further supported by documented associations between PCOS and autoimmune conditions, such as the presence of antinuclear antibodies (ANA) seen in SLE and anti-thyroid peroxidase (anti-TPO) antibodies linked to Hashimoto thyroiditis." (PMID 39932461, 2025). "A 2023 systemic review and meta-analysis on the possible benefits of Se on Hashimoto thyroiditis provided conservative evidence for supplementing patients with Hashimoto thyroiditis with Se over 6 months by demonstrating an associated decrease in thyroid peroxidase and thyroglobulin antibodies." (PMID 39408290, 2024). "Abnormal levels of TPO-Ab and TG-Ab can cause autoimmune hypothyroidism." (PMID 36743954, 2023). "The basis of the development of AITD - Hashimoto’s thyroiditis (HT), Graves’ disease (GD), Graves’ ophthalmopathy (GO) is the loss of immune tolerance to thyroid antigens - thyroid peroxidase (TPO), thyroglobulin (Tg) and thyroid-stimulating hormone receptor (TSH-R)." (PMID 37711890, 2023). "Autoimmune thyroid diseases (AITD), mainly Hashimoto’s thyroiditis (HT) and Graves’ disease (GD), are a consequence of loss of immune tolerance toward organ-specific self-antigens, including thyroglobulin (TG), thyroperoxidase (TPO), and the receptor for TSH1." (PMID 35140214, 2022). "Autoimmune hyperthyroidism, also known as Graves’ disease (GD), is associated with TSH-receptor antibodies (TRAb), whereas autoimmune hypothyroidism, also known as Hashimotos’ thyroiditis, is associated with thyroid peroxidase (TPO) and thyroglobulin (Tg) antibodies." (PMID 34034778, 2021). "Hashimoto’s thyroiditis (HT) is the most prevalent cause of chronic hypothyroidism in iodine sufficient regions, which stems from an autoimmune response against thyroid peroxidase (TPO) and/or thyroglobulin (Tg)." (PMID 33142736, 2020). "Strikingly, autoimmune hypothyroidism (Hashimoto disease, HT) associated with anti-TPO and anti-Tg antibodies was detected in almost 50% of the patients with hypovitaminosis D (44.7% in the vitamin D deficient group and 47.6% of the vitamin D insufficient women)." (PMID 31824513, 2019). "Anti-TPO antibodies are associated with Hashimoto thyroiditis." (PMID 27274883, 2016). "Furthermore, there is expansion of immune response toward endogenous thyroid antigen, that is, the thyroid peroxidase and thyroglobulin which consequently cause extensive lymphocytic infiltration leading to Hashimoto's thyroiditis." (PMID 24198979, 2013). "The hallmark in the diagnosis of Hashimoto thyroiditis is the presence of TPO autoantibodies." (PMID 21172028, 2010). "While there's a strong associationbetween the presence of anti-TPO antibodies and Hashimoto's thyroiditis, it remainsuncertain whether the elevated levels of anti-TPO or anti-Tg antibodies directlycause the condition or merely indicate ongoing disruption of thyroid cells." (PMID 39224552, 2024). "The authors likely assumed that Hashimoto’s thyroiditis is hypothyroidism, although the same diagnostic criteria of Hashimoto’s thyroiditis are also applied in GD, namely hypoechogenicity of the thyroid parenchyma and abundance of antibodies to thyroid peroxidase (TPOAb) and thyroglobulin (TGAb)." (PMID 38737666, 2024). "Furthermore, Zhangbi Wu66 indicated that TPO‐Ab induces a non‐receptive endometrial milieu in the euthyroid state, which may underlie the detrimental effects of Hashimoto's thyroiditis (HT) itself on embryo implantation." (PMID 32198952, 2020).
Hashimoto thyroiditis (continued). "Thyroid microsomal antibodies, namely, anti-TPO antibody, is a thyroid autoantibody targeting thyroid peroxidases and is considered diagnostic of both Grave's disease and Hashimoto's thyroiditis, while in Hashimoto's thyroiditis, anti-TPO antibody is reported in approximately 90% of patients." (PMID 31428301, 2019). "However, the proportion of patients in whom such IgE autoantibodies can be detected is limited, and TPO-specific IgE autoantibodies are generally associated with the more common TPO IgG autoantibodies that characterize patients with Hashimoto’s thyroiditis which are found in a minority of patients." (PMID 28751972, 2017). "The lack of data on the effect of L-thyroxine (LT-4) doses on the level of anti-TPO and anti-TG antibodies in Hashimoto's thyroiditis and the relationship with anthropometric measurements resulted in the desire to fill this niche." (PMID 41682650, 2026). "The search terms included "Hashimoto's thyroiditis", "Hashimoto's disease", "levothyroxine", "L-thyroxine", "anti-TPO", "anti-TG", "anti-thyroid antibodies"." (PMID 42278392, 2026). "Curcumin supplementation, when combined with an anti‐inflammatory diet, was associated with reductions in waist circumference, waist‐to‐hip ratio, and serum anti‐TPO levels in patients with Hashimoto's thyroiditis." (PMID 41329567, 2026). "The diagnosis of Hashimoto's thyroiditis relies on clinical presentation, thyroid function tests, detection of anti-thyroid peroxidase and anti-thyroglobulin antibodies, and ultrasound imaging." (PMID 41717291, 2026). "Anti-TPO antibodies are specific for the autoantigen TPO and they are the most common anti-thyroid autoantibody found in approximately 90% of Hashimoto’s thyroiditis, 75% of Graves’ disease, and 10-20% of nodular goitre or thyroid carcinoma cases." (PMID 40937419, 2025). "Increased serum levels of TPO antibodies and Tg antibodies were suggestive of autoimmune hypothyroidism." (PMID 41321897, 2025). "Our results further revealed that anti-TPO levels in Hashimoto’s thyroiditis patients are significantly higher than in the control group (P<0.001)." (PMID 40060227, 2025). "The TPO levels which was more that 600 on 27.10.22 was reduced to 180 on 9.2.24 which shows the inflammatory activity due to Hashimoto's thyroiditis has also reduced." (PMID 40886522, 2025). "The prevalence of anti-TPO positivity (78.8%) observed here is notably higher than in some earlier Indian studies, suggesting a rising trend of autoimmune hypothyroidism in the Indian population." (PMID 41280993, 2025). "Selenium, in particular, has been shown in multiple trials to reduce anti-TPO titers by 20–40% over a 3–6 month period in patients with Hashimoto’s thyroiditis." (PMID 41465826, 2025). "Hashimoto’s thyroiditis is an autoimmune disease, and elevated anti-TPO is detected nearly in all affected patients." (PMID 40095713, 2025). "Selenium supplementation in Hashimoto’s thyroiditis appears to enhance the activity of selenoproteins, leading to reduced local inflammatory reactions and a decrease in anti-TPO antibody production, ultimately improving the structure of the thyroid." (PMID 41157173, 2025). "Anti thyroid peroxidase antibody level was >600 IU/ml, confirming the presence of Hashimoto's thyroiditis." (PMID 40886522, 2025). "As demonstrated by Piticchio’s meta-analysis, a gluten-free diet, which is a diet that has been extensively studied in the context of Hashimoto’s disease, has been shown to reduce anti-TPO levels." (PMID 41228460, 2025). "In conclusion, Hashimoto’s thyroiditis is associated with impaired segmental and global longitudinal LV strain, and this impairment is correlated with TIMP-1 and anti-TPO levels, indicating the involvement of cardiac tissue beyond the thyroid gland." (PMID 40095713, 2025).